BCL2 (BCL2 apoptosis regulator)
Diseases named in the same sentence as BCL2 in open-access papers (continued):
Sharing a sentence is not in itself a finding about the gene and the disease.
diffuse large B-cell lymphoma (252 papers, 2008 to 2026). "And other therapeutic target is BIRD-2, which also targets the BH4 domain of Bcl-2, has defined that causing the Ca2+ overload and opening the mPTP, resulting the death of the diffuse large b-cell lymphoma (DLBCL) and chronic lymphocytic leukemia (CLL) cell." (PMID 40661148, 2025). "MYC/BCL2 double expression (DE) is associated with poor prognosis in patients with diffuse large B-cell lymphoma (DLBCL) receiving rituximab, cyclophosphamide, doxorubicin, vincristine, and prednisolone (R-CHOP)." (PMID 38485822, 2024). "High BCL2 expression has been reported in hematological malignancies and diffuse a large B-cell lymphoma, and the A allele is linked to greater BCL2 expression." (PMID 36831357, 2023). "BCL2 is an antiapoptotic factor, and overexpression of BCL2 is reported to be associated with poor prognosis in diffuse large B cell lymphoma." (PMID 33160404, 2020). "In typically MYC-driven Burkitt lymphoma, 7% (5/70) carry Notch1 mutations, 8% (5/63) of BCL2-associated diffuse large B-cell lymphoma (DLBCL) carry similar PEST mutations of Notch2, and 6% (2/35) had amplification of the Notch2 locus." (PMID 24959528, 2014). "In addition, it was suggested high BCL2 expression were associated with unfavourable prognostic in diffuse large B-cell lymphoma." (PMID 27677077, 2016). "Since Bcl-2 translocation is a hallmark for follicular lymphomas, we hypothesized that Bcl-2 family proteins have a role in protecting human diffuse large B cell lymphomas against SFK inhibition induced apoptosis." (PMID 20043832, 2009). "Limited data about the prognostic significance of BCL2 mutations and BCL2 copy number variations in diffuse large B-cell lymphoma (DLBCL) are available." (PMID 34806851, 2021). "BCL2 overexpression has been reported to be associated with poor prognosis in patients with diffuse large B-cell lymphoma (DLBCL)." (PMID 32606309, 2020). "Positive expression of BCL2 has been associated with unfavorable survival in extranodal diffuse large B-cell lymphomas (DLBCL) and MALT lymphomas." (PMID 26064133, 2015). "The pathogenic mechanisms underlying double-expressor diffuse large B-cell lymphoma (DE-DLBCL), specifically related to the myelocytomatosis oncogene (MYC) and B-cell lymphoma 2 (BCL2), are not yet fully understood." (PMID 40426926, 2025). "Significant enrichment of “stromal-1” signatures was observed in BCL2(-) diffuse large B-cell lymphoma." (PMID 40484962, 2025). "Prognostic analysis reveals that the expression levels of CDK6, BCL2, and DNMT3B are closely associated with the prognosis in human diffuse large B-cell lymphoma." (PMID 39864628, 2025). "Histopathological examination diagnosed a triple-expressor gastric Diffuse Large B-Cell Lymphoma (DLBCL) [Bcl-2 focal (60%), Bcl-6 focal (40%), C-Myc (10%), CD10 focal (70%)]." (PMID 38997875, 2024). "Abdominal CT scan and contrast-enhanced imaging suggested a left adrenal mass lesion, and percutaneous needle biopsy of the adrenal mass lesion confirmed diffuse large B-cell lymphoma (with dual expression of C-myc and Bcl-2 proteins)." (PMID 38518055, 2024). "Bcl-2 is one of the most widely studied genes in haematological malignancies, especially in diffuse large B-cell lymphoma (DLBCL)." (PMID 37756103, 2023). "Bcl‐2 rearrangement and translocation also exist in 15%–20% of diffuse large B‐cell lymphoma (DLBCL) patients." (PMID 38090056, 2023). "For example, BM-1197, a molecules that targeted Bcl-2 and inhibited the role of this protein on apoptosis, has been developed for the treatment of Diffuse large B cell lymphoma (DLBCL)." (PMID 37345122, 2023). "In line with our findings in ALL, a recent study also found heterogeneous sensitivity of diffuse large B-cell lymphoma cells to inhibitors of BCL-2, BCL-XL and MCL-1." (PMID 35031695, 2022). "Myc/Bcl2 co-expression was confirmed as vital prognostic factors in primary central nervous system diffuse large B cell lymphoma." (PMID 35013138, 2022).
diffuse large B-cell lymphoma (continued). "A 66-year-old Caucasian man was diagnosed with aggressive medullary high-grade Diffuse large B-cell lymphoma (DLBCL) with a BCL2 amplification based on marrow histology." (PMID 35501493, 2022). "Nevertheless, the overall Bcl-2-protein levels remained extremely low in these MDA-MB-231 cells, when benchmarked against the Bcl-2-protein levels present in OCI-LY-1 cells, a Bcl-2 dependent diffuse large B-cell lymphoma cell line." (PMID 34750538, 2022). "More importantly, prior research has illustrated that Bcl2 and Myc are co-expressed in diffuse large B cell lymphoma cells and their higher expression is accountable for the poorer outcome of cancer." (PMID 35013138, 2022). "Correlation with known diffuse large B-cell lymphoma markers showed that high expression of MYC, BCL2, and ENO3 was associated with worse outcome." (PMID 36358737, 2022). "A 52‐year‐old male was diagnosed with diffuse large B‐cell lymphoma (DLBCL) with BCL2, BCL6, and MYC translocations (triple hit lymphoma)." (PMID 35846047, 2022). "Fusions involving the immunoglobulin (IG) loci and one of BCL2, BCL6, or MYC are hallmark aberrations of diffuse large B-cell lymphoma and are hard to detect owing to the poor mappability of the IG loci." (PMID 33441414, 2021). "In a study published in 2019, a class of molecular high-grade diffuse large B-cell lymphoma (MHG) was defined, which had significantly higher mutation frequencies than GCB in KMT2D, BCL2, MYC, or DDX3X." (PMID 34925435, 2021). "According to our results, it was concluded that Apigenin synergizes with Abivertinib to induce apoptosis in diffuse large B-cell lymphoma by down-regulating BCL2, BCL-XL and activating the caspase family." (PMID 32127939, 2020). "A diagnosis of diffuse large B-cell lymphoma in our therapeutic era should be implemented by the definition of the cell of origin, additional immunohistochemistry (i.e., BCL2 and MYC), and by fluorescent in-situ hybridization." (PMID 33050534, 2020). "Diffuse large B-cell lymphoma (DLBCL) with MYC/BCL2 double-expression (DE), a recently proposed poor prognostic group, can be easily identified by immunohistochemistry in routine clinical practice." (PMID 33182440, 2020). "Cancer cells such as chronic lymphocytic leukemia (CLL) and diffuse large B-cell lymphoma (DLBCL) exploit the antiapoptotic effects of Bcl-2 to survive oncogenic stress, though such cells are primed to death." (PMID 32943617, 2020). "Bcl-2 was highly expressed in diffuse large B-cell lymphoma cell lines and expressed at low levels in Burkitt and Jurkat cells." (PMID 31892356, 2019). "Numerous studies have investigated the prognostic values of MYC and/or BCL2 protein overexpression in diffuse large B-cell lymphoma (DLBCL)." (PMID 29674626, 2018). "BCL-2 and functionally redundant counterpart, MCL-1, are frequently over-expressed in high-risk diffuse large B-cell lymphoma (DLBCL)." (PMID 29269870, 2017). "Many of these pairs (such as miR-15 b/BCL2 in apoptosis or BART-6/BCL6 in diffuse large B-cell lymphomas) were experimentally discovered and/or computationally predicted." (PMID 25858286, 2015). "A proportion of MYC translocation positive diffuse large B‐cell lymphomas (DLBCL) harbour a BCL2 and/or BCL6 translocation, known as double‐hit DLBCL, and are clinically aggressive." (PMID 27347428, 2015). "The identified association among FOXP1, BCL2, and BCL6 indicates the possibilities of uncovering the development process in diffuse large B-cell lymphoma tumor cells." (PMID 23289441, 2013). "Accordingly we found that all the human diffuse large B cell lymphoma cells had abundant expression of Bcl-2 and Bcl-xL proteins compared to two murine immature B lymphoma cell lines." (PMID 20043832, 2009). "Similarly, although overexpression of the cell cycle regulator MYC and the anti-apoptosis protein BCL2 has prognostic value in the systemic diffuse large B-cell lymphoma, their significance in PCNLS remains uncertain." (PMID 39803131, 2024).
diffuse large B-cell lymphoma (continued). "c-MYC and BCL2 positivity are important prognostic factors for diffuse large B-cell lymphoma." (PMID 38243330, 2024). "This study revealed that patients with primary thyroid diffuse large B cell lymphoma who received combination immunochemotherapy with radiotherapy had a better prognosis and Myc/Bcl-2 protein co-expression, treatment modalities, and rituximab were independent prognostic factors." (PMID 32982962, 2020). "Though BCL6 could suppress BCL2 in diffuse large B-cell lymphoma, we found that the expression of these two proteins exhibits positive correlation in glioblastoma cells." (PMID 30420967, 2018). "The isolated MYC+/BCL6+/BCL2− subset, more frequent in germinal center B-cell like diffuse large B-cell lymphoma, had significantly better survival compared with the isolated MYC+/BCL2+/BCL6− subset (more frequent in activated B-cell like diffuse large B-cell lymphoma)." (PMID 26573234, 2016). "In addition, both in MM and Bcl-2 diffuse large B-cell lymphoma ABT-737 was reported to induce autophagy and this ABT-737-induced autophagy was cytoprotective." (PMID 25008202, 2014). "Therefore, we studied the effect of TAT-IDPS in a more heterogeneous Bcl-2-dependent cancer model using a set of ‘primed to death' diffuse large B-cell lymphoma (DL-BCL) cell lines containing elevated Bcl-2 levels." (PMID 23681227, 2013). "Initial histopathological examination of the resected lesion, due to aberrant expression of B-cell markers (PAX-5, CD79a, c-Myc, Bcl-2), led to a misdiagnosis of diffuse large B-cell lymphoma (DLBCL)." (PMID 41561755, 2025). "Previously, we demonstrated that BAPTAi enhanced apoptosis induced by venetoclax, a BCL-2 antagonist, in diffuse large B-cell lymphoma (DLBCL)." (PMID 37684238, 2023). "Another study showed that Bcl-2 expression correlated very well with the sensitivity of the BCL-2 inhibitor venetoclax in various diffuse large B-cell lymphoma (DLBCL) cell lines." (PMID 36553549, 2022). "Diffuse large B-cell lymphoma (DLBCL) patients with MYC/BCL2 double expression (DE) show poor prognosis and their clinical outcomes after R-CHOP therapy vary immensely." (PMID 33182440, 2020). "Several cancer cell types, including chronic lymphocytic leukemia (CLL) and diffuse large B-cell lymphoma (DLBCL) upregulate antiapoptotic Bcl-2 to cope with oncogenic stress." (PMID 32943617, 2020). "This study was designed to analyze the clinical characteristics and prognostic value of c-MYC and BCL-2 proteins expression in patients with primary central nervous system diffuse large B-cell lymphoma (PCNS-DLBCL)." (PMID 31702637, 2019). "In diffuse large B-cell lymphoma (DLBCL), overexpression of the anti-apoptotic protein BCL-2 is correlated with adverse survival in patients treated with standard rituximab, cyclophosphamide, vincristine, doxorubicin, and prednisone (R-CHOP)." (PMID 31801186, 2019). "Anti-apoptotic Bcl-2 over-expression has been reported in several human cancers, including prostate cancer, diffuse large B-cell lymphoma (DLBCL), melanoma, etc., resulting in protection of cancer cells from apoptosis or inhibition of TRAIL-induced apoptosis." (PMID 27019364, 2016). "An ultrasound-guided biopsy of intra-abdominal lymph nodes showed diffuse large B-cell lymphoma stage IIIb, that was CD20 +, Bcl-2 + and Mum-1 + by IHC." (PMID 41306534, 2025). "Fourteen years after initial diagnosis, she developed CNS symptoms with cerebellar lesions; resection revealed transformed diffuse large B-cell lymphoma (DLBCL) of germinal center origin (CD5+, CD10+, BCL2, BCL6, MYC+, Ki-67 ~70%)." (PMID 41146768, 2025). "Moreover, a recent study in diffuse large B cell lymphoma (DLBCL) showed that active super-enhancers (SEs) harboring hypermutation are linked to the upregulation of oncogenes related to B cell developmental and malignant transformation, including BCL6, BCL2, and CXCR4." (PMID 39724337, 2025).
diffuse large B-cell lymphoma (continued). "Diffuse large B‐cell lymphoma typically expresses pan‐B markers CD19, CD20, CD22, CD79a, CD45RA, PAX5 markers, and other markers CD10, BCL6, BCL2, MYC, and MUM‐1." (PMID 40735721, 2025). "The tumor exhibited high proliferative activity and co-expression of BCL2 and MYC, consistent with a “double expressor” diffuse large B-cell lymphoma (DLBCL)." (PMID 40767831, 2025). "A 52-year-old woman was diagnosed with primary mediastinal of differentiation CD20 (+), CD79a (+), Bcl-2 (+), Bcl-6 (partial+), MUM1 (partial+) diffuse large B cell lymphoma (DLBCL) almost six months prior." (PMID 38561816, 2024). "Moreover, in diffuse large B-cell lymphoma (DLBCL), an aggressive form of non-Hodgkin lymphoma, high levels of eIF4B increase the expression of key survival proteins, including BCL-2, DAXX and ERCC5, and are prognostic of poor patient outcome." (PMID 39225047, 2024). "Follicular lymphoma (FL), CLL, one-third of diffuse large B-cell lymphoma (DLBCL), mantle cell lymphoma (MCL) and Waldenstrom macroglobulinemia (WM) exhibit aberrant BCL-2 expression." (PMID 39906657, 2024). "Double-hit diffuse large B-cell lymphoma (DH-DLBCL) is an aggressive, and often refractory, type of B-cell non–Hodgkin lymphoma (NHL) characterized by rearrangements in MYC and BCL2." (PMID 37882668, 2023). "Increased abundance of anti-apoptotic BCL-2, BCL-XL or MCL-1 is found in several B-cell malignancies, including diffuse large B-cell lymphoma (DLBCL), thereby counteracting pro-apoptotic signaling induced by oncogenic stress." (PMID 37684238, 2023). "Double expressor lymphoma (DEL), defined as overexpression of BCL2 and MYC, is an aggressive subtype of diffuse large B cell lymphoma (DLBCL)." (PMID 34123811, 2021). "The mass was later diagnosed as a diffuse large B cell lymphoma with double expressor (C-MYC+ and Bcl-2+)." (PMID 32040778, 2021). "Ideal lead compounds and candidate drugs with inhibitory effect on BCL2 were screened from ZINC database, which laid a foundation for drug development and compound improvement of drug treatment for diffuse large B-cell lymphoma (DLCBL)." (PMID 34259934, 2021). "In diffuse large B-cell lymphoma (DLBCL) cell lines, inhibitors of mTOR, PI3K, Bcl-2, and chemotherapeutic agents were reported to show synergistic activity when combined with ibrutinib." (PMID 32404973, 2020). "In diffuse large B-cell lymphoma (DLBCL), concomitant overexpression of BCL-2 and MYC is classified as a “double-hit” DLBCL, which is associated with a dismal prognosis, high risk for relapse, resistance to standard chemotherapy and justifies upfront escalation to more intensive treatment." (PMID 32131385, 2020). "These genes may be expressed in diffuse large B-cell lymphoma (DLBCL), but the role of BCL-2 in its prognosis has been contradictory, and OCT-1 has yet to be tested." (PMID 33121489, 2020). "We performed FISH analyses for c-Myc, BCL2 and BCL6 genes to subclassify diffuse large B-cell lymphoma on cases received after the 2017 WHO edition." (PMID 32992679, 2020). "Different malignancies, including B-cell cancers such as diffuse large B-cell lymphoma (DLBCL), are characterized by overexpression of the anti-apoptotic Bcl-2 protein." (PMID 29899382, 2019). "Histological examination of the specimen provided a diagnosis of diffuse large B-cell lymphoma (DLBCL) with immunohistochemistry staining showing positive results for CD20, CD79, Bcl-2 and Bcl-6." (PMID 31752767, 2019).
diffuse large B-cell lymphoma (continued). "Expression of the anti-apoptotic B-cell lymphoma 2 (BCL-2) protein in patients with diffuse large B-cell lymphoma (DLBCL) strongly correlates with resistance to standard therapy with cyclophosphamide, vincristine, doxorubicin, prednisolone, and rituximab (R-CHOP)." (PMID 31801186, 2019). "For example, in diffuse large B-cell lymphoma (DLBCL) and chronic lymphocytic leukemia (CLL), Bcl-2 is important for cancer cell survival by limiting IP3R activity and regulating IP3 signaling." (PMID 30842340, 2019). "Although diffuse large B cell lymphoma (DLBCL) cells widely express the BCL2 protein, they rarely respond to treatment with BCL2-selective inhibitors." (PMID 30404918, 2018). "This study investigates the protein expression of C-MYC, BCL-2, and BCL-6 in diffuse large B-cell lymphoma (DLBCL) and their relationship with genetic abnormalities." (PMID 30666200, 2018). "In this study, we assessed rearrangements and expression of MYC, BCL2 and BCL6 in 898 patients with de novo diffuse large B-cell lymphoma treated with standard chemotherapy (cyclophosphamide, doxorubicin, vincristine, and prednisone plus rituximab)." (PMID 26573234, 2016). "Double-hit B cell lymphoma (DHL) is defined as diffuse large B cell lymphoma with translocations and/or extra signals involving MYC along with BCL2 and/or BCL6 as identified by FISH." (PMID 25918657, 2015). "The adverse prognostic significance of double expressor (DE) status—defined by co‐expression of MYC and BCL2—and double‐hit/triple‐hit (DH/TH) status—characterized by translocations involving MYC and BCL2 and/or BCL6—is well established in nodal diffuse large B‐cell lymphomas." (PMID 41151993, 2026). "MYC translocation occurs in 8–14% of diffuse large B-cell lymphoma (DLBCL), and may concur with BCL2 and/or BCL6 translocation, known as double-hit (DH) or triple-hit (TH)." (PMID 38184753, 2024). "Bcl-2 is a pivotal regulator of apoptosis, often overexpressed in various cancers, including chronic lymphocytic leukemia (CLL), diffuse large B-cell lymphoma (DLBCL), breast cancer, and lung cancer, allowing cancer cells to evade apoptosis, leading to chemoresistance and poor prognosis." (PMID 39274842, 2024). "Clinical trials with single-agent venetoclax/ABT-199 (anti-apoptotic BCL2 inhibitor) revealed that diffuse large B-cell lymphoma (DLBCL) is not solely dependent on BCL2 for survival." (PMID 38893249, 2024). "Pharmacological inhibition of SRC-3 with gambogic acid reduced tumor growth of diffuse large cell b cell lymphoma (DLBCL) models in vitro and in vivo through histone deacetylation and downregulation of multiple oncoproteins such as Bcl-2, cyclin D3, Bcl-6, and c-Myc." (PMID 38683834, 2024). "Diffuse large B-cell lymphoma (DLBCL) is a heterogeneous disease, with a variable response to chemotherapy depending on, and not limited to, cell of origin, double/triple hit, or MYC/BCL-2 co-expression status." (PMID 37641153, 2023). "Likewise, in B-cell malignancies, proto-oncogenes are often translocated to the locus of the immunoglobulin heavy chain (IGH), such as MYC in Burkitt lymphoma (IGH/MYC), CCND1 in mantle cell lymphoma, BCL-6 in diffuse large B-cell lymphoma (DLBCL) and BCL-2 in follicular lymphoma." (PMID 35563017, 2022). "The genes BCL2 and MDM2 are also upregulated in lymphoid neoplasm diffuse large B-cell lymphoma." (PMID 34422220, 2021). "MYC/BCL2 protein co-expression (i.e., double expressor) has been shown to be a negative predictor of outcome in diffuse large B-cell lymphoma (DLBCL)." (PMID 34282799, 2021). "CKD-581 treatment also up-regulated the phosphorylation of histone H2AX (γH2AX, DNA double-strand break marker), and reduced levels of MYC and anti-apoptotic proteins such as BCL-2, BCL-6, BCL-XL, and MCL-1 in DH/DE-diffuse large B cell lymphoma (DLBCL) cell lines." (PMID 32575557, 2020).